CXCR4 (C-X-C motif chemokine receptor 4)
Diseases named in the same sentence as CXCR4 in open-access papers (continued):
Sharing a sentence is not in itself a finding about the gene and the disease.
cancer (continued). "In the search for suitable protein agents that might promote endosome escape, we have explored the translocation domain (TD) of the diphtheria toxin as a functional domain in CXCR4-targeted oligomeric nanoparticles designed for cancer therapies." (PMID 36559138, 2022). "It is expected that various antagonists of CXCR4 could also be used to impair the development of cancer cell migration." (PMID 34976180, 2022). "The CXCR4/CXCL12 and CCR5/CCL5 axes, both related to HIV, have been associated with the early (epithelial–mesenchymal transition and invasion) and late events (migration and metastasis) of cancer progression." (PMID 36613922, 2022). "However, the expression of CXCR4 levels in primary cancers and metastases are inconsistent from different studies due to the lack of systematic investigation and quantification." (PMID 35145271, 2022). "Studies have shown that CXCR4 could stimulate cancer progression by dominating the RhoA/ROCK pathway." (PMID 36612163, 2022). "Moreover, cancer cells hijack this system by overexpressing CXCR4, allowing for rapid metastasizing to distant organs with high CXCL12 expression." (PMID 35788730, 2022). "HIF-1α is the key regulator of the cellular response to hypoxia and is involved in hypoxia-induced chemokine receptor CXCR4 up-regulation and increased migratory activities in different cells, such as mononuclear phagocytes, endothelial cells, and cancer cells." (PMID 35634326, 2022). "We also tested if this nanotoxin was able to selectively eliminate CXCR4+ target cancer cells and whether this could lead to effective antitumor and antimetastatic activity." (PMID 35532120, 2022). "Moreover, the immune predictive model was constructed by CXCR4-related immunomodulators to help the individualization therapy of cancer patients." (PMID 35388021, 2022). "Other clinical trials are also ongoing in cancer patients with CXCR4." (PMID 35158948, 2022). "Therefore, it is becoming recognized emerging that the CXCL12/CXCR4/CXCR7 axis represents a potential target for cancer treatment." (PMID 34976180, 2022). "The CXCL12/CXCR4 biological axis plays a unique role in a variety of diseases and cancers." (PMID 35893797, 2022). "Cancer cells acquire resistance to chemotherapy through the emergence of genetic mutations or epigenetic changes, favoring the activation of signaling pathways related to chemotaxis, cell survival or proliferation, including the CXCL12/CXCR4 axis." (PMID 35532120, 2022). "Of note, CXCR4 and integrin αvβ3 had a synergistic effect on cancer metastasis." (PMID 36145541, 2022). "However, CXCR4 can also prevent adequate infiltration of T cells into tumors, as the surrounding CXCL12-rich stroma can arrest CXCR4-expressing T cells from directly reaching carcinoma cells." (PMID 33603130, 2022). "Treatment outcomes are not yet universal, but one theory shows that this might be mediated through carcinoma-associated fibroblasts (CAF), which also influence the CXCR4/CXCL12 axis." (PMID 36059606, 2022). "Moreover, the reduction in P2Y11 expression by siRNA decreased cancer cell migration and abolished the impact of ATPγS on cell migration and CXCR4 expression." (PMID 34503103, 2021). "Interestingly, CXCL12 secretion through osteocytes functions as a chemoattractant and helps in homing and retention of CXCR4 expressed cancer cells in the BM microenvironment." (PMID 34975909, 2021). "Recent data suggested that targeting the cancer associated genes was proved as novel strategies to improve drug sensitivity, but the role of CXCR4 in regulating cisplatin-sensitivity has not been investigated." (PMID 34180759, 2021). "CXCR4 is undoubtedly a widely explored chemokine receptor with respect to cancer imaging." (PMID 34500609, 2021). "In addition, transwell assays demonstrated that NANOG regulates cancer cell migration through the SDF1/CXCR4 pathway." (PMID 34638956, 2021).
cancer (continued). "Similarly, CXCL12 increased phosphorylation of p38 MAPK and SAPK in cancer cells co-expressing CXCR4 and CXCR7." (PMID 34298991, 2021). "It has been known that CXCL12/CXCR4 axis plays a pivotal role in the neurotropism of cancer cells." (PMID 34170080, 2021). "The macrophage migration inhibitory factor (MIF) expressed by the RMS cell line interacts with CXCR4 and CXCR7 (RMS cell surface receptors) in the paracrine loop, which can reduce the number of cancer-associated fibroblast infiltration, increase cell adhesion, and promote blood vessel formation." (PMID 34838000, 2021). "Interestingly, an analysis of patient samples showed that CXCR4+ cancer cells were located at the invasive front of the tumors, in intimate contact with the stroma." (PMID 33530455, 2021). "In spite of the evidence that CXCR4 may be involved in docetaxel-resistance regulation, a direct link from CXCL12 by macrophage to CXCR4 in the cancer cells cannot be confirmed." (PMID 34069563, 2021). "Targeting the interleukin-33/CXCR4 signaling circuit attenuated cancer aggressiveness and may have potential as a treatment strategy for improving the prognosis of HNSCC patients." (PMID 34298657, 2021). "Based on the role of Nanog in cancer stem cells, our results provide a novel connection between CXCR4 and cancer stemness that may be beneficial for improving the decisions in the selected therapy." (PMID 34638956, 2021). "In conclusion, our results suggest that the role of NANOG in cancer stem cell migration may be due to the direct regulation of the CXCR4 gene." (PMID 34638956, 2021). "CXCR4 is known as a major receptor in various biological processes, including leukocyte migration, maintenance of hematopoietic stem cell niches, tissue development, and cancer metastasis." (PMID 34527817, 2021). "In addition, AMD3100 has been used as a chemical tool to demonstrate that small molecule antagonism of CXCR4 is a promising strategy for the treatment of different cancers, such as breast cancer, prostate cancer, and ovarian cancer." (PMID 34684878, 2021). "Therefore, in the current study involving GBM, we started with the study of BIRC5 (one of the rare genes differentially expressed in normal and cancer cells) and CXCR4 (gene involved in the survival and proliferation of CSCs)." (PMID 34685742, 2021). "However, blockade of CXCL12-CXCR4 signaling axis by inhibitors like Nox-A12, FDA approved CXCR4 inhibitor drug AMD3100 have shown limited clinical success in cancer treatment." (PMID 33966046, 2021). "The two receptors of CXCL12, CXC receptor 4 (CXCR4) and atypical chemokine receptor 3 (AKRC3, also known as CXCR7), are expressed on PDAC cells, and an elevated expression of CXCR4 is associated with a poor prognosis in several cancer types." (PMID 35008248, 2021). "Relative to the normal esophageal epithelium, 392 (46.3%) and 494 (52.1%) cancer-specific SEs were recovered in the EC and LNC H3K27ac profiles, respectively, and these SEs were enriched with cancer-associated genes or oncogenes, such as CCND125,26, CWH43, ANO1, and CXCR4." (PMID 34294701, 2021). "In addition, CXCR4 also plays an important role in the chemotherapy resistance of a variety of malignant tumors." (PMID 34759953, 2021). "As the PPARγ ligand RGZ has been shown to interfere with this axis in other solid tumors, we evaluated whether the CXCL12/CXCR4 axis might contribute in mediating the ACC anti-cancer activity of RGZ in different ACC cell lines." (PMID 34834449, 2021). "Furthermore, the CXCL12/CXCR4 axis has been found to play an important role in anti-PD-1 resistance in other cancer types." (PMID 34911533, 2021). "Within the hematopoietic system CXCR4 is expressed on most hematopoietic cell types including lymphocytes, stromal fibroblasts, endothelial and epithelial cells as well as hematopoietic stem cells and cancer cells." (PMID 33273682, 2021).
cancer (continued). "Indeed, clinical trials targeting CXCR4 in cancer patients with different drugs alone or in combination with ICT are ongoing (NCT02104427, NCT01359657)." (PMID 33988305, 2021). "This supports the theory that CXCR4 in cancer cells might be one of the critical docetaxel-resistance regulators and is potentially involved in CXCL12 (macrophage)/CXCR4 (cancer cell) crosstalk." (PMID 34069563, 2021). "The mRNA of CXCR4 was prominently upregulated in cancer cells with CTNND1 knockdown, suggesting that it might be regulated at the transcription level." (PMID 34830862, 2021). "Recent review articles related to C-X-C motif chemokine ligand 12 (CXCL12)-chemokine receptor type 4 (CXCR4)/ chemokine receptor type 7 (CXCR7) axis are focused on cancers in general, however, our focus in this review is to summarize the role of this axis in CRC progression and metastasis." (PMID 34298991, 2021). "Based on the published information that CXCR4 participates in the regulation of cancer metastasis, we explored whether CXCR4 also had similar regulating effects on the ccRCC cells." (PMID 34180759, 2021). "Moreover, we demonstrate that NANOG regulates CXCR4 expression and promotes cancer cell migration through the SDF1/CXCR4 pathway." (PMID 34638956, 2021). "CXCR4 and IL-6 are key-regulators of inflammation and leucocyte migration in immunity and cancer and could potentially play a role in systemic immunity." (PMID 34417915, 2021). "Therefore, further clinical trials investigating the efficacies and safeties of CXCR4 antagonists are urgently needed in the context of advanced cancers." (PMID 33463063, 2021). "Our results suggest that S1P4 signaling modulation may be a promising target for anti-CXCR4 cancer immunotherapy." (PMID 34504486, 2021). "CXCR4 pathway has been certificated to influence EMT of cancer cells in vitro." (PMID 34170080, 2021). "Other relevant factors in this context could be the overexpression of CXCR4 on cancer stem cells, which are believed to represent a drug-resistant cell population." (PMID 33579381, 2021). "It was suggested that SDF-1/CXCR4 axis could promote the dissemination of cancer cells towards sites highly secreting SDF-1." (PMID 33838662, 2021). "This, however, needs careful in-depth validation, also including a careful selection of cancer patients who might profit from such an approach (e.g., cancers with negligible tumoral CXCR4 expression)." (PMID 34885030, 2021). "CXCR4 is one of the most well-known chemokine receptors with proliferative, survival, and migration effects that are shown to be aberrantly expressed in many cancers and are involved in metastasis." (PMID 34943797, 2021). "This inhibitory effect of miR‐146a‐5p/-193a-5p restoration on the migration of cancer cells may occur through their effects on various genes involved in migration, including CXCR4, E-cadherin, ROCK, and C-Myc." (PMID 34888223, 2021). "CXCR4 is a pan-cancer G-coupled receptor expressed in both solid and haematological malignancies." (PMID 33546207, 2021). "The exploration of EPI-X4 as a ligand of the tumoral marker CXCR4 allows the exploitation of a novel humanized tool, and it also offers realistic possibilities for the development of a new generation of safe and stable drugs for targeted cancer therapy." (PMID 34208189, 2021). "Importantly, the CXCL12/CXCR4 axis has been identified as a target for drugs in human tumors due to its critical role in promoting and maintaining cancer stem cells." (PMID 33579381, 2021). "For example, a CXCR4-directed PET/CT could help to visualize receptor-positive cancer stem cells that are considered to be in particular resistant to radiation or chemotherapy." (PMID 33579381, 2021). "In addition, CXCR4 has a role in cancer metastasis via activating the mitogen-activated protein kinase (MAPK) pathway." (PMID 34589582, 2021). "Cancer stromal cells in PDAC abundantly express C-X-C Motif Ligand 12 (CXCL12)—A ligand of CXCR4." (PMID 33546207, 2021).
cancer (continued). "However, NF157 at a lower concentration also had a significant effect on the inhibition of cancer cell migration, and this concentration has a lesser effect on CXCR4 expression." (PMID 34503103, 2021). "Interestingly, CXCR4 knockdown in all the cases markedly induces the expression of DR5 across various cancer cell lines of human origin." (PMID 33966046, 2021). "As a result, CXCL12/CXCR4 axis plays a crucial role in cancer and could serve as a target for cancer therapy." (PMID 33962657, 2021). "CXCR4 has been shown to co-localize with CRC stem cell markers, such as Lgr5, CD133, and CD44, which are thought to be associated with the epithelial-mesenchymal transition process and resistance to cancer drug therapy." (PMID 35582377, 2021). "Thus far, CXCR4 has been a major target for the therapy of different cancers, either by blocking antibodies or small molecules, among them BKT140, bicyclam AMD070, AMD3100, AMD11070, MSX-122, GSK812397, KRH-3955, and several small modified peptides." (PMID 34944943, 2021). "Chemokine CXCL12 and its receptor CXCR4 are promising therapeutic targets for cancer management." (PMID 33456563, 2021). "Simultaneous blockade of CXCR4 and E-selectin could exclude dormant metastatic cancer cells from the protective bone marrow environment and block their re-entry into niches, preventing recurrence." (PMID 35006432, 2021). "Besides well-established IL-33/ST2 and SDF1/CXCR4 (stromal-derived factor 1/C-X-C motif chemokine receptor 4) signaling, the CAF-induced IL-33 upregulated CXCR4 via cancer cell induction of IL-33 self-production." (PMID 34298657, 2021). "So far, the interest has focused on cancer and on drugs that block CXCR4-initiated signaling; we suggest that small molecules that activate CXCR4 signaling or can dissect the effects on cell migration and proliferation may be as useful." (PMID 32983169, 2020). "This is evidenced by studies showing elimination of cancer cells with CXCR4 inhibitor monotherapy." (PMID 33014834, 2020). "Flow cytometry analysis was performed to check whether the three anti-CXCR4 scFvs could bind to cancer cells." (PMID 33392074, 2020). "CXCR4 is the most commonly found chemokine receptor in human cancer cells." (PMID 32850457, 2020). "Chemokine CXCL12 and its receptor CXCR4 are constitutively overexpressed in human cancers." (PMID 31802362, 2020). "However, it was additionally reported as an agonist that recruited β-arrestin-2 to CXCR7 and was shown to block the transendothelial migration of CXCR4+/CXCR7+ human cancer cells, a similar result seen with CXCL11." (PMID 32098047, 2020). "For instance, CXCL12-elicited bone pain induced by cancer while siRNA or inhibitor of CXCR4, a CXCL12 receptor, could antagonize CXCL12-elicited pain in spinal neurons." (PMID 32434423, 2020). "In this context, DPP-4 could cleave/inactivate CXCL12 and downregulate the CXCL12/CXCR4 axis, subsequently inhibiting cancer cell growth, invasiveness and metastasis." (PMID 31991851, 2020). "Some cancer therapeutics was developed to target CXCR4/CXCL12 signaling pathways." (PMID 33392074, 2020). "In addition, IFN-γ contributes to the formation of a metastatic niche by transforming cancer stem cells to metastatic cancer stem cells through the induction of the chemokine receptor, namely CXCR4, which enhances their migratory and invasive potential." (PMID 33005420, 2020). "Cancer cells are thought to hijack the CXCR4/CXCL12 axis to establish distant metastasis." (PMID 32232002, 2020). "In addition, increasing evidence showed that CXCR4 not only plays a marked role in cancer metastasis but also in cancer stem cells." (PMID 33363463, 2020). "Besides the most-studied plerixafor, many other CXCR4 antagonists have been applied and tested in various types of cancer." (PMID 32079173, 2020). "Increasing evidence showed that SDF-1/CXCR4 signaling was correlated to cancer." (PMID 32362830, 2020).
cancer (continued). "The authors concluded that CXCR4 might be a potential biomarker, particularly of inflammatory diseases such cancer." (PMID 32867211, 2020). "Thus, CXCL12 and its receptor CXCR4 were thought to represent a promising therapy targeting the link between cancer cells and stromal cells." (PMID 32972006, 2020). "The chemokine receptor CXCR4 is overexpressed in different cancer cells." (PMID 33392074, 2020). "Moreover, CXCL12 is highly expressed in liver and specifically attracts melanoma and CXCR4 (+) cells, thereby increasing cancer liver metastasis." (PMID 33363463, 2020). "Notably, BCAF-derived SDF-1 enhances cancer cell migration by binding to the receptor CXCR4 expressed on cancer cells." (PMID 32604738, 2020). "Moreover, CXCR4 is a major receptor driving cancer metastasis, and not only the CXCR4/CXCL12 but also the CXCR4/MIF axis has been implicated in this process." (PMID 33239628, 2020). "Increased levels of CXCR4 are present in cancer cells compared to the normal cells." (PMID 32983169, 2020). "CXCR4 is one of the most prevalent chemokine receptors ubiquitously expressed in cancer cells." (PMID 32972006, 2020). "AMD3100, a CXCR4 inhibitor, induced rapid T-cell accumulation around cancer cells in mice." (PMID 33381115, 2020). "Clinical evidence related to this topic requires further evaluation; one may be aware of choosing the proper diabetic medicine for cancer-bearing patients, especially patients with chemoresistance and CXCR4-positive cancers." (PMID 31991851, 2020). "In addition, ESCC cells coexpressing CD133 and CXCR4 possess the characteristics of cancer stem cells and contribute to poor prognosis of patients." (PMID 32742450, 2020). "CXCR4 is endowed with potent chemotactic properties for leukocytes but is also highly expressed in a variety of cell types, including endothelial and epithelial cells, hematopoietic stem cells, stromal fibroblasts, and cancer cells." (PMID 32784523, 2020). "Therefore, the blocking of the CXCR4/CXCL12 axis is an important approach in order to inhibit cancer metastasis in therapy." (PMID 32486408, 2020). "Therefore, higher CXCL12 levels in response to DPP4 inhibitor treatment can be relevant to the metastasis of CXCR4-positive cancers." (PMID 32498358, 2020). "Indeed, it is known that the osteotropism of CXCR4 + cancer stem cells depends on their ability to follow the CXCL12 gradient towards the bone marrow." (PMID 33238004, 2020). "Therefore, CXCR4-positive cancer stem cells are likely to be attracted to the peripheral vessels, thereby serving as a pool for metastasis." (PMID 33363463, 2020). "These anti-CXCR4 scFvs may become potential anti-cancer therapeutics for the treatment of different cancers." (PMID 33392074, 2020). "Importantly, the CXCR4 has emerged as a drug target for its crucial role in promoting and maintaining cancer stem cells (CSCs)." (PMID 32232002, 2020). "In this regard, its covalent binding with the genotoxic antimetabolite Floxuridine (FdU) efficiently and selectively eliminates CXCR4+ cancer stem cells, thus preventing metastases and also inducing the regression of already stablished metastases with no toxicity in non-target tissues." (PMID 33105866, 2020). "SDF-1α also binds to its own conventional receptor, CXCR4, involving in homeostatic modulation such as development and immune surveillance as well as pathological conditions such as inflammation, ischemia, and cancers." (PMID 33292475, 2020). "The CXCR4/CXCL12 axis plays a crucial role in cancer metastasis." (PMID 32486408, 2020). "Several miRNAs (miR-25-3p, miR-130b-3p, miR-425-5p) upregulated in CRC cells by the CXCL12/CXCR4 axis could be transferred to macrophages via exosomes inducing M2 polarization of macrophages that promoted cancer metastasis by enhancing EMT." (PMID 32708431, 2020). "CXCR4 is expressed in a great variety of cell types, including lymphocytes, hematopoietic stem cells, endothelial cells, epithelial cells, stromal fibroblasts, and cancer cells." (PMID 32260318, 2020).